ACE (angiotensin I converting enzyme)
Diseases named in the same sentence as ACE in open-access papers (continued):
Sharing a sentence is not in itself a finding about the gene and the disease.
depression (continued). "For the ACE polymorphism rs4646994, ANOVA showed different mean HADS-depression scores among the three genotypes at 24-month follow-up." (PMID 32367400, 2020). "With regard to the significant higher ACE promoter methylation frequency in depressed patients it seems probable that these epigenetic mechanisms have a higher impact on depression than on healthy controls." (PMID 22808171, 2012). "However, the precise nature of the relationship between the ACE genotype and depression remains a subject of ongoing debate, necessitating further investigation." (PMID 40367215, 2025). "However, in the current study, ACE genotype appears to be of relatively low importance in predicting the severity of depression." (PMID 40367215, 2025). "Surprisingly, when the 313 patients were classified by sex, the ACE I/D polymorphism only influences the therapeutic outcome in women with major depression, not men." (PMID 36761172, 2022). "A cursory literature search reveals physiological arguments that the renin‐angiotensin system (on which ACE inhibitors act) plays an important role in mood disorders, as well as case studies dating back to the 1980s of ACE inhibitors appearing to treat major depression." (PMID 35689299, 2022). "Therefore, in this study we used genotyping data from a prospective, multicenter trial to evaluate the association between persisting depression and the two I/D polymorphisms in the SLC6A4 and ACE gene located on chromosome 17." (PMID 32367400, 2020). "However, the role of the ACE gene polymorphism and the connection between depression and oxidative stress have not been extensively studied, although there is a link between oxidative stress and depression." (PMID 39009760, 2024). "The angiotensin converting enzyme (ACE), a member of the renin-angiotensin system (RAS) has been repeatedly discussed both as a major candidate gene for depression and as a common susceptibility factor for the bi-directional relation between depression and cardiovascular disorders (CVD)." (PMID 22808171, 2012). "Therefore it seems probable that epigenetic alterations of the ACE gene in terms of hypermethylation might contribute to the dysregulated PLN in depression, at least in a subgroup of patients." (PMID 22808171, 2012). "Animal studies on mood disorder models, either depression or mania, were focused on the reversal of behavioral and/or cognitive symptoms through the inhibition of RAS components like the ACE, AT1, or Mas receptors." (PMID 37953501, 2024). "ACE Inhibitors (ACEIs), which target the renin-angiotensin system (RAS), are thought to offer protective benefits for cognition, depression, and anxiety." (PMID 39184138, 2024). "Compared to ACE-II homozygous and ACE-ID heterozygous females, among ACE-DD homozygous females, positive β values for PANSS depression factor indicated greater decreases of this variable." (PMID 36293037, 2022). "ACE inhibitors can, therefore, effectively reduce inflammatory mediators, such as IL-6 and CRP, and play a role in improving depression, anxiety, and other adverse emotions." (PMID 35527821, 2022). "Out of our 26-analyte panel, only three proteins (ApoH, ApoA1 and B2M) were altered in bipolar disorder patients and four (MIF, ACE, TNC and ILra) were changed in patients with depression." (PMID 26171982, 2015). "The ACE/Ang II/AT1R classical pathway aggravates depression and anxiety by activating AT1R, while the non-classical pathway exerts anxiety/antidepressant effects by activating MasR." (PMID 36761172, 2022). "Depletion of ACE2 and the subsequent imbalance of the ACE/ACE2 metabolic pathways may thus impair both serotonin and dopamine synthesis, resulting in higher rates of mental “fog,” depression, and anxiety in COVID-19 patients." (PMID 34648616, 2022).
depression (continued). "Interestingly, BDNF emerged among the genes shared by depression and atherothrombosis, and it was well-connected to all the genes identified in both databases, namely, IL-1β, IL-6, IL-18, TNF, APOE, ACE, MTR, MTHFR genes." (PMID 35911513, 2022). "Therefore, the inhibition of the ACE/Ang II/AT1 receptor system could potentially represent a novel therapeutic target for depression." (PMID 37312182, 2023). "Based on the results, ACE and ANG II may be hidden depression recurrence-related factors that may not be affected by traditional antidepressants, even though we could not determine a direct link between the ANG II and depression recurrence." (PMID 29069807, 2017).
pneumonia (61 papers, 2005 to 2025). An acute, acute and chronic, or chronic inflammation focally or diffusely affecting the lung parenchyma, caused by an infection in one or both of the lungs (by bacteria, viruses, fungi, or mycoplasma.). "ACE2 has high homology with ACE, and in some reports, the ACE inhibitor has been shown to have the effect of slowing down the infection and damage of pneumonia risk." (PMID 33671652, 2021). "ACE inhibitors have been reported that can decrease pneumonia risk through their main mechanism of action." (PMID 33598195, 2021). "Genotype DI of ACE I/D polymorphism is associated with the infectious rate particularly severe pneumonia in this study conducted in the Turkish population." (PMID 34603503, 2021). "In a population-based study, the 90-day risk for hospitalization with pneumonia was also reduced in patients over 65 years of age with a new prescription of antihypertensive drugs if the prescribed drugs were ACE inhibitors of angiotensin receptor blockers." (PMID 35498160, 2021). "A meta-analysis that included 19 studies noted that patients taking ACE inhibitors were associated with a significant approximately one-third reduction in the risk of pneumonia compared with controls." (PMID 34490373, 2021). "GLZ seems to be an alternative ACE inhibitor that can decrease pneumonia risk through inhibiting ACE‐2 expression and alleviating allergies in their respiratory systems." (PMID 33598195, 2021). "A closer look at the association between the use of ACE inhibitors and the risk of pneumonia-related mortality has been the subject of several publications for more than 20 years." (PMID 32635289, 2020). "Recent studies have shown that the use of statins and/or angiotensin-converting enzyme (ACE) inhibitors prior to admission is associated with decreased mortality in patients hospitalized with pneumonia." (PMID 24489672, 2014). "Prescription for ACE inhibitors was associated with a lower risk of hospital admission with pneumonia (adjusted OR 0.61, 95% CI0.46 to 0.81)." (PMID 25353172, 2014). "Compared to calcium channel blockers, ACE inhibitors (adjusted OR 0.61, 95% CI 0.46 to 0.81) and ARBs (adjusted OR 0.52, 95% CI 0.36 to 0.76) were associated with a lower risk of pneumonia." (PMID 25353172, 2014). "Conditional logistic regression was used to estimate the odds ratio (OR) for pneumonia associated with use of ACE inhibitors and ARBs." (PMID 23912052, 2013). "We found that use of ACE inhibitors was associated with a decrease in pneumonia risk (ORs = 0.85; 95% CI = 0.44–1.65); however, due to the small number of cases (n = 527), the finding was not statistically significant." (PMID 23912052, 2013). "This is because ACE activity directly affects the cough reflex in older patients, and this effect was negatively associated with pneumonia risk, particularly in older individuals with ACE II/ID genotypes." (PMID 22723835, 2012). "Our findings provide further support to other studies that demonstrate that ACE inhibitor use is associated with decreased mortality for patients with pneumonia." (PMID 16159398, 2005). "Chronic treatment with ACE inhibitors may increase the risk, while the use of active vitamin D may reduce the risk of developing severe pneumonia." (PMID 35336859, 2022). "ACE inhibitors can decrease pneumonia risk through their main mechanism of action." (PMID 33598195, 2021). "The abnormalities of the ACE system in hypertensive and diabetic patients, potentially associated with the chronic use of ACE inhibitors, could predispose to a massive increase in lung bradykinin leading to rapidly progressing pneumonia." (PMID 33472675, 2021). "Given these heterogeneous results, we conducted the current study to characterize the 90-day risk for hospitalization with pneumonia in a large population of older adults initiated on ACE inhibitors, ARBs, beta blockers (BB) or thiazides in a routine outpatient care setting." (PMID 25353172, 2014).
pneumonia (continued). "Recent studies have shown that use of angiotensin-converting enzyme (ACE) inhibitors may decrease pneumonia risk in various populations." (PMID 23912052, 2013). "The severity of pneumonia and acute respiratory failure is positively correlated with age-dependent disequilibria of the ACE/ACE2 ratio." (PMID 32719619, 2020). "At the beginning of the 2000s, a series of randomized controlled trials demonstrated that patients on ACE inhibitors had a decreased incidence of pneumonia." (PMID 32635289, 2020). "A recent study reported that the use of an ACE inhibitor can alleviate pneumonia in stroke patients by reducing the effects of Ang II on the brain as well as substance P and bradykinin metabolism." (PMID 33232272, 2020). "Similar to previous studies, we observed a significant reduction in pneumonia rates in patients prescribed an ACE inhibitor." (PMID 25353172, 2014). "Specifically, there is a growing body of literature demonstrating a reduced incidence of pneumonia in patients treated with angiotensin converting enzyme (ACE) inhibitors." (PMID 25353172, 2014). "Our aim was to examine the association between the use of beta-blockers, statins, angiotensin converting enzyme (ACE) inhibitors, and angiotensin II receptor blockers (ARBs) with pneumonia-related outcomes." (PMID 24489672, 2014). "Both statins and ACE inhibitors have been demonstrated to blunt systemic inflammatory responses, which are also triggered in pneumonia." (PMID 24489672, 2014). "Our study adds to the growing body of literature surrounding ACE inhibitor use and its potential to curb the incidence of pneumonia." (PMID 25353172, 2014). "The differential diagnosis of persistent dry cough is broad and includes upper respiratory tract infection (“common cold”), allergic asthma, psychogenic cough, drug side effects (ACE inhibitors), (atypical) pneumonia, and lung cancer." (PMID 23984170, 2013). "We investigated the effect of ACE inhibitors and angiotensin II receptor blockers (ARBs) on pneumonia hospitalization in the general population of Taiwan." (PMID 23912052, 2013). "Even though Angiotensin Converting Enzyme (ACE) inhibitors were associated with lower pneumonia-related mortality, the data is not convincing." (PMID 40098935, 2025). "Evidence shows that angiotensin-converting enzyme (ACE) activity is altered in pneumonia and ARDS." (PMID 39593182, 2024). "Several studies have shown considerable association between ACE genotype (as observed with variable prevalence in different ethnic populations) and various disease endpoints such as sepsis, ARDS, and risk of pneumonia." (PMID 35498160, 2021). "Compared to control treatments, both ACE inhibitors (7 studies) and ARBs (1 study) were associated with a decrease in pneumonia-related mortality, without differences in intervention." (PMID 32635289, 2020). "They concluded that the best evidence available pointed towards a putative protective role of ACE inhibitors, but not ARBs, in risk of pneumonia." (PMID 32635289, 2020). "There are several potential reasons that these medications may be protective against pneumonia-related mortality besides the demonstrated cardioprotective effects of statins, ACE inhibitors, and ARBs." (PMID 24489672, 2014). "In conclusion, cardiovascular medications such as statins, ACE inhibitors, and ARBs, were associated with decreased mortality in patients hospitalized with pneumonia but not cardiovascular events." (PMID 24489672, 2014). "Recently, a meta-analysis of randomized and non-randomized studies demonstrated a reduced risk of pneumonia in ACE inhibitor users." (PMID 25353172, 2014). "While not fully understood, the proposed mechanism by which ACE inhibitors may protect against pneumonia is related to improvement in both cough and swallowing reflexes, an effect thought to be mediated through increased levels of substance P and bradykinins." (PMID 25353172, 2014).
pneumonia (continued). "Both ACE inhibitors and ARBs reduced the incidence of pneumonia related hospitalization." (PMID 25353172, 2014). "Specifically, by reducing the inflammatory response, ACE inhibitors and ARBs may reduce the severity of pneumonia, thereby preventing pneumonia related hospitalization." (PMID 25353172, 2014). "Finally, there is a paucity of literature surrounding the biologic rationale for a reduction in the incidence of pneumonia with both ACE inhibitors and ARBs." (PMID 25353172, 2014). "Neither the use nor cumulative dose of ACE inhibitors or ARBs was associated with pneumonia among the Taiwanese general population." (PMID 23912052, 2013). "In our judgment, ACE inhibitors may have a preventive effect on pneumonia in certain populations, such as people with impaired cough reflex." (PMID 23912052, 2013). "A total of 128 patients (0.15%) initiated on an ACE inhibitor and 43 patients (0.13%) initiated on an ARB were hospitalized with pneumonia in the subsequent 90 days." (PMID 25353172, 2014). "A positive correlation was also detected between the TNF-α rs1800629 A allele and sepsis, while a negative correlation was detected with the ACE rs1799752 insertion genotype and the severity of pneumonia." (PMID 37630611, 2023). "In our study, the use of ACE inhibitors and ARBs in patients with COVID-19 pneumonia was higher than in COVID 19 patients without pneumonia." (PMID 32599972, 2020). "The same results were obtained in our study—the expression of ACE in the severe form of pneumonia was absent, while in the case of pneumonia of moderate severity (case 2) the ACE-2 expression was weak and related mainly to single cells of the epithelium and endothelium." (PMID 37109672, 2023). "The authors believe this is due to the following reasons: biological ones such as the variations in angiotensin-converting enzyme (ACE)-2 receptor expression (whose verification is out of the scope of this study) and timely health care access for those who present complications such as pneumonia." (PMID 34660475, 2021). "We hypothesized that a reduction in the incidence of pneumonia would be seen with both ACE inhibitors and ARBs when compared to the CCBs, but no benefit would be seen with thiazides or BBs." (PMID 25353172, 2014). "In addition, there was no dose–response effect of ACE inhibitors or ARBs on pneumonia requiring hospitalization." (PMID 23912052, 2013). "Thus, our data suggests that beneficial effects of statin, ACE inhibitors, and ARBs on mortality in patients admitted with pneumonia may not be due to prevention of future cardiac events, but other mechanisms." (PMID 24489672, 2014). "However, the effect of ACE inhibitors on pneumonia was not significant among a general population." (PMID 23912052, 2013).
end-stage renal disease (55 papers, 2002 to 2026). "Thus, combined antialdosterone and ACE inhibitor therapy may offer new avenues of treatment, in particular for CKD with nephrotic range proteinuria unresponsive to ACE inhibitor alone who are at highest risk of progression to end stage renal disease (ESRD)." (PMID 27713239, 2010). "Treatment of micro-albuminuria or proteinuria with angiotensin-converting enzyme (ACE) inhibitors or angiotensin receptor blockers (ARBs) may slow the progression of CKD to end-stage renal disease (ESRD)." (PMID 23637835, 2013). "We observed a trend towards better response to ACE inhibitors in Caucasian DD carriers compared to II carriers, in terms of blood pressure, proteinuria, glomerular filtration rate, ACE activity and progression to end-stage renal failure." (PMID 16242049, 2005). "For patients with some of the earlier clinical symptoms or even before, genetic diagnosis could mean preventive treatment such as using ACE inhibitors which could delay the onset of end-stage renal failure and improve life expectancy, even when begun before the onset of proteinuria." (PMID 26934356, 2016). "Despite superior BUN levels and improved antiproteinuric and antifibrotic potential of dual blockade, lifespan prior to end-stage renal failure was not significantly improved by dual therapy (ACE+Spiro) with a mean survival of 89.3 ± 17.6 days." (PMID 34209341, 2021).